CD4 (CD4 molecule)
Diseases named in the same sentence as CD4 in open-access papers (continued):
Sharing a sentence is not in itself a finding about the gene and the disease.
infection (continued). "R5 macrophage-tropism is associated with an increased envelope:CD4 affinity that partly results from an increased exposure of CD4 contact residues on gp120 and allows the use of low levels of CD4 for infection." (PMID 20507591, 2010). "The selective advantage of escape mutations is higher during early infection and wanes later as a result of the decline in both CD8 T cell numbers and function and changes in CD4 T cell target cells." (PMID 20862289, 2010). "In a recent paper, we have shown that in CXCR4-tropic SHIV-infected monkeys vaccination significantly reduced peak viral load and increased the lowest CD4+ T cell count in the acute phase of infection." (PMID 21152101, 2010). "The delicate balancing between control of infection and prevention of immunopathology is attributed to CD4+CD25+FoxP3+ regulatory T cells (Tregs), which play an important role in maintaining immune homeostasis and controlling excessive immune responses." (PMID 20224778, 2010). "Regarding the cell cycle, the known HTLV-1-dependent recruitment of infected CD4+ cells into the cell cycle appears restricted to the persistent infection while in vitro infection has been found to trigger CD8+ cell cycling." (PMID 20222966, 2010). "Two weeks post-infection, absolute CD4+ T cell numbers in PBMC were decreased in the high (p = 0.002) and middle (p = 0.06) dose groups, whereas the low dose group experienced a modest decrease by four weeks post-infection that was not significant." (PMID 20085648, 2010). "We previously showed that opsonization of HIV-1 with complement enhanced infection of epithelial cells, and also enhanced infection of dendritic cells and viral transfer to CD4 T cells in a CR3 and DC-SIGN-dependent manner." (PMID 20546571, 2010). "It is expressed early during infection and functions to accelerate endocytosis of cell surface CD4 by a clathrin/AP-2 pathway, followed by delivery of the internalized CD4 to the multivesicular body pathway for eventual degradation in lysosomes." (PMID 20442859, 2010). "Productive infection was observed only in U87.CD4.CCR5 cells, suggesting that SHIV-1157ipEL uses CCR5 as an exclusive co-receptor for entry." (PMID 20657739, 2010). "We show that these memory CD4+ T cells persist in an activated state, produce the inflammatory cytokines TNFα and IFN-γ, and are more protective than “resting” memory CD4+ T cells obtained from mice in which the infection has been eliminated." (PMID 21124875, 2010). "Both HCV-specific IFN-γ-producing CD8+ T cell response and a strong proliferative CD4+ T-cell response are generated during the first 6 months after infection." (PMID 21047421, 2010). "Like CD40L activation, LPS stimulation also induces high secretion of C-C chemokines and TNFα and inhibits infection of macrophages and CD4+ T cells with R5 HIV-1 strains." (PMID 20380696, 2010). "Infection with feline immunodeficiency virus (FIV) results in a progressive immune-dysfunction characterized by a gradual decline in helper (CD4+) T lymphocytes." (PMID 20420700, 2010). "The study confirms and extends previous analyses of in vitro infection of T cell lines, or of CD4+ T cells in vivo that were performed on a limited number of individuals." (PMID 20195503, 2010). "The amount of p24 measured in the samples served as readout since a reduced infection of the CD4+ T cells indicates an anti-viral effect by the generated CD8+ cells." (PMID 20442876, 2010). "To address this possibility, we infected HHD mice with LASV, and prior to infection depleted either CD8+ T cells or CD4+ T cells or both using monoclonal antibodies." (PMID 20360949, 2010). "HIV can infect both cDCs and pDCs, and has been found to initiate infection in both DC subsets more efficiently than in other cell types (including macrophages and CD4+ T cells) in vitro." (PMID 20937128, 2010). "Polyfunctional CD4+ T cell responses have been correlated with optimal protection against infection in vivo." (PMID 20478058, 2010).
infection (continued). "In accordance, intense CD4+ T cell infiltration during infection can be seen throughout the genital tract." (PMID 21079691, 2010). "During the acute stage of infection large numbers of resting and memory CD4 T cells disappear from the lymphoid tissues and mucosal layers, particularly in the gut, by direct infection and by bystander effects." (PMID 20824126, 2010). "Intriguingly, there is also evidence that Schistosoma blood flukes exploit CD4+ T cell responses, by co-opting the activities of CD4+ T cells during pre-patent infection to promote parasite development and subsequent reproduction." (PMID 21078176, 2010). "In this respect all groups agree that both endocytosis and infection are prevented by inhibitors of the CD4-gp120 interaction, and this is consistent with earlier work investigating cell-free viral endocytosis into T cells." (PMID 21994681, 2010). "An increase in the numbers of CD4+ T cells was observed in the lungs and dLN of IL-10−/− mice at day 29 after infection with Mtb as compared with controls." (PMID 20518032, 2010). "HIV-1 infected macrophages showed effective cell survival (green cells) for 12 days in the absence of SNP and perifosine (media alone), which is contrasted to the HIV-1 infected CD4+ T cells known to undergo cell death within a few days post infection." (PMID 20927348, 2010). "In order to investigate CD4+ T cell differentiation during infection, we carefully dissected the UGT, which consisted of the uterus and uterine horns, from the cervix and proximal vaginal tissue of the LGT, for analysis by RT-PCR." (PMID 21079691, 2010). "We then considered inferred coreceptor usage as a function of time since infection, clinical stage, CD4 counts, HIV viral load, and V1V2 length, both overall and separately in plasma- and PBMC–derived viruses." (PMID 21187897, 2010). "While the levels of CD4+ T cells decreased slightly at 4 weeks post-infection, those of CD8+ T cells increased slightly at this time, relative to pre-infection." (PMID 20824205, 2010). "Recently we isolated and identified palmitic acid (PA) as a novel natural small molecule that inhibits HIV-1 fusion and infection by the mechanism of binding to the CD4 receptor and blocking gp120-to-CD4 attachment." (PMID 20730055, 2010). "In this regard, the majority of infection studies have experimentally manipulated Tregs based on surrogate markers such as CD25 expression on CD4+ T cells." (PMID 20714351, 2010). "Depleting CD4+ T cells in this group resulted in impaired resistance and 1.5–3 log more bacteria throughout infection demonstrating a clear involvement of CD4+ T cells also in the protection promoted by prior i.n. infection with MoPn." (PMID 20505822, 2010). "Protective immunity to most fungal infections requires adaptive immune responses involving CD4+ T-cells, as evidenced by the susceptibility of HIV-patients to infections with fungal pathogens such as Candida and Cryptococcus." (PMID 21075040, 2010). "Jurkat cells were transfected with viral vectors and incubated for 24 h before adding an equal number of Raji/CD4 target cells and infections were quantitated by luciferase assay 48 h after the start of coculture." (PMID 20195464, 2010). "We compared memory CD4 T cells generated and maintained in chronic infection, with those that survived after drug-clearance of infection." (PMID 21124875, 2010). "The importance of CD4+ T cells in this infection has been demonstrated by the fact that C. rodentium infection is fatal in mice lacking CD4+ T cells." (PMID 20532209, 2010). "Features of the HIV-1 cycle in macrophages still need to be better established but appear to be different at many steps from what is known during infection of CD4+ T cells (see accompanying reviews in the present issue of Retrovirology)." (PMID 20374631, 2010).
infection (continued). "To further investigate the nature and location of CD4+ T cell subsets during infection, we undertook RT-PCR analysis of T helper cell differentiation by monitoring transcription factor mRNA expression in the genital tract." (PMID 21079691, 2010). "For CD4+ cells, experimental in vitro infection had only modest effects on cell cycling and apoptosis while our experiments confirmed and extended the known positive effect of infection on CD4+ cell cycling in vivo." (PMID 20222966, 2010). "Recently, it has also been suggested that simultaneous priming and infection of T cells by DCs is the main driving force behind the early infection dynamics, when activated CD4+ T cell numbers are low." (PMID 20360840, 2010). "Of significance it has recently been demonstrated that during L. major infections high local arginase levels at the site of infection mediate L-arginine depletion, which results in impaired local CD4+ T cell function particularly IFN-γ production." (PMID 21085614, 2010). "Our data strengthen evidence that Gag-Env interaction is important in envelope association with lipid rafts containing GPI-anchored proteins for efficient assembly onto mature virions resulting in productive infection of primary CD4+ T cells." (PMID 20064199, 2010). "It is reasonable to presume that correct or nearly correct folding occurred for both MIP1α and CD4 when displayed on Caulobacter, given the ability to bind specific antibodies and the infection blocking activity noted." (PMID 20442778, 2010). "Animals in both groups experienced a transient depletion of CD4+ T cells during the acute infection, with a rebound to near baseline levels as they progressed towards the chronic infection." (PMID 20459829, 2010). "• Significant levels of infection and destruction observed even within days of infection for memory CD4+ cells." (PMID 20875154, 2010). "Our results also showed that the concentration of IFN-α was significantly positively correlated with the CD4+ T-cell counts but negatively correlated with viral load through the infection." (PMID 21118577, 2010). "In comparison, an intranasal infection with C. muridarum induced a T cell response that consisted predominantly of TNFα/IFN-γ co-expressing effector CD4+ T cells and an antibody response consisting of C. muridarum specific IgG1, IgG2a but also IgA." (PMID 20505822, 2010). "This is the first study from an industrialized country to show a faster CD4 cell decline and higher rate of subsequent virological failure with subtype D infection." (PMID 20205896, 2010). "On the contrary, the proportion of cells left uninfected after in vitro infection and within the S phase of the cell cycle was significantly higher than that of uninfected CD4+ cells derived from TSP/HAM (10.3 versus 5.1, p = 0.004, Mann Whitney test)." (PMID 20222966, 2010). "We link the novel finding that WTA can stimulate CD4+ T cells to the development of staphylococcal SSTIs in an in vivo infection model." (PMID 20949105, 2010). "While it is desirable to examine cell-to-cell infection using primary T-cells as targets, we have been unable to detect Luc transduction in cocultures of transfected Jurkat T-cells and activated CD4+ T-cells." (PMID 20195464, 2010). "Early during infection, IFN-γ is secreted by NK cells and other cell types, as part of the innate response, and later on the infection course by activated CD4+ and CD8+ T cells." (PMID 20442858, 2010). "The average CD4 counts for patients with multiple versus single strain infection were similar, and patients with multiple strains had a wide range of baseline CD4 counts." (PMID 21143966, 2010). "As depletion of CD4+ T cells occurs early following infection with SIVmac239, treatment with tenofovir was initiated ten days after viral inoculation." (PMID 20824092, 2010). "LVS infection resulted in a distinct increase in IL-17A+ producing cells both in CD4+ T and γδ T cell populations." (PMID 20585449, 2010).
infection (continued). "Plasma levels of CD4+ cells are partially reconstituted after the first infection period, but then decrease continuously." (PMID 20109174, 2010). "In order to assess Th1 differentiation ex vivo, we purified CD4 T cells from spleens 10 days after infection and restimulated them with plate-bound antibodies against CD3 or a combination of CD3 and CD28 at different concentrations." (PMID 20668698, 2010). "Loop lengths and PNLGS were examined as a function of time since infection, CD4 count, viral load, and calendar year in cross-sectional and longitudinal analyses." (PMID 21187897, 2010). "We next tried to identify HLA-matched subjects in order to characterize the specific CD4+ T cell response against the F protein during HCV natural infection." (PMID 21151917, 2010). "Although the absolute numbers of both cell types increased in parallel with the absolute numbers of splenocytes, a progressive and steady increase in percent CD4+ T cells became readily apparent beginning week three post-infection." (PMID 20714351, 2010). "Previous results indicate that DCIR can capture HIV-1 on DCs, enhance de novo virus production by DCs (i.e. infection in cis), and increase DC-mediated virus transmission to CD4+ T cells (i.e. infection in trans)." (PMID 21085612, 2010). "CM CD4+ T cell functions, such as proliferation and IL-2 secretion, are impaired as early as the primary infection stage in progressive HIV infection, and are only partially recovered in efficiently treated patients." (PMID 20195518, 2010). "Cytolytic control of SHIV89.6P infection cannot simultaneously explain the observed relationships between peak viral load, decay of viral load after the peak and CD4+ T cell depletion at nadir." (PMID 21152101, 2010). "In macaques infected with SIV, intestinal CD4+ T cells are almost entirely depleted within three weeks of infection." (PMID 20485497, 2010). "Vpu is expressed at later stages of infection and acts by targeting newly-synthesized CD4 in the ER for degradation by cytosolic proteasomes." (PMID 20442859, 2010). "We observed a drop in CD4+ cells at both 3 and 6 weeks post-infection in both groups compared to uninfected animals." (PMID 20700454, 2010). "At enrollment, the mean CD4 count was 502±276 cps/ml (range, 30–1,815), and the mean lowest reported CD4 count during the course of infection was 244±188 (range, 0–1,038)." (PMID 20098616, 2010). "This rigorous approach has previously identified CD4+ T-cell counts, and serum IL-6 concentrations as independent predictors of infection." (PMID 20090932, 2010). "In previous work, we demonstrated that CD4+ T cells are essential in controlling infection by the extracellular bacterial pathogen Ye in mice and that Ye modulates DC functions of BM-DCs in vitro, leading to inhibition of T-cell proliferation." (PMID 21124820, 2010). "We found that OVA-specific CD4+ T cells had a reduced potential to proliferate when stimulated with OVA after infection with Ye compared to control mice." (PMID 21124820, 2010). "To investigate an association between KI and WU polyomavirus (KIPyV and WUPyV) infections and CD4+ cell counts, we tested HIV-1–positive patients and blood donors." (PMID 20735940, 2010). "Dendritic cells (DCs) play a critical role in HIV transmission by efficiently binding virus particles, migrating to lymph nodes, and transmitting them to CD4+ T cells, a process called trans-infection." (PMID 20617179, 2010). "We show that CD4+ T cells with phenotypic characteristics of memory cells are indeed generated within two months of an infection." (PMID 21124875, 2010). "The multiple levels at which Vpu acts to prevent export of CD4 from the ER underscore the importance of ensuring complete suppression of CD4 for progression of the infection." (PMID 20442859, 2010). "Despite these changes in suppressive potency, the percentage of Tregs among bulk and Salmonella FliC-specific CD4+ T cells each remained relatively constant throughout infection." (PMID 20714351, 2010).
infection (continued). "The infection, which has been ignited with a relatively small number of virions, then spreads to other tissue types harbouring immune system cells, such as CD4+CCR5+CCR3+ microglia and macrophages, or hMR+ astrocytes, megakaryocytes and monocytes." (PMID 20967291, 2010). "Infections carried out with HTLV-1 vectors in Jurkat-Raji/CD4 coculture had all of the characteristics expected for cell-to-cell infection." (PMID 20195464, 2010). "Intranasal administration of γHV68 to mice establishes an acute lytic infection in lung epithelial cells, which is normally controlled by day 13 postinfection via the anti-viral activities of CD4 and CD8 T cells." (PMID 20181071, 2010). "In recent years there has been a paradigm shift in our understanding of HIV pathogenesis, stemming from the recognition that the earliest targets of infection are mucosal memory CD4+ T cells." (PMID 21994702, 2010). "Access to second-line ART regimens in LMIC is problematic, mainly because of the expense of HIV protease inhibitors (PI), and CD4 monitoring is often the sole surrogate marker available to guide the management of the infection." (PMID 21060792, 2010). "CD4+ T cells are of fundamental importance for protection against C. trachomatis genital tract infections, yet a detailed understanding of functional qualities of CD4+ T cell subsets during infection is limited." (PMID 21079691, 2010). "In contrast, the CD4+ T cell response to schistosome worms during the pre-patent phase of infection has been characterized as a Th1 response." (PMID 21078176, 2010). "Then, the same amount of virus (normalized by p24 gag levels) was used to infect C8166 CD4+ T cells, and the level of infection was monitored by measuring the luciferase activity." (PMID 20331877, 2010). "Similar results were obtained upon infection of CD4-positive primary T-cells with an EGFP-expressing virus." (PMID 20950436, 2010). "We and others have shown that CD4+ T cells are crucial for clearance of a primary infection with C. trachomatis from the genital tract and the development of protective immunity." (PMID 21079691, 2010). "• A very rapid and very significant decline in CD4+ counts, exceeding 25% after four weeks of infection." (PMID 20875154, 2010). "Second, there is infiltration of individual infected CD4+ cells or virions into pockets of uninfected target cells that generate local foci of infection in the seminal tract, giving rise to clonal amplification of virus in this compartment." (PMID 20808902, 2010). "To determine an association between infection with KIPyV and WUPyV and CD4+ cell counts, we obtained plasma samples from HIV-1–positive patients having high and low CD4+ cell counts and a group of healthy controls and tested them for these 2 polyomaviruses." (PMID 20735940, 2010). "In the gut, naïve and central memory T cells are supplied, but these cells are short-lived and only partially substitute for the CD4+ effector memory T cells depleted during the acute phase of infection." (PMID 20569472, 2010). "Infection of naïve PBMC with ZEBOV in vitro strongly upregulates Fas/FasL expression on CD4 and CD8 T lymphocytes and also TNF-related apoptosis-inducing ligand (TRAIL) mRNA expression in the same cells." (PMID 20957152, 2010). "In the Jurkat-Raji/CD4 coculture system, infection is measured 48 h after cell mixing, as this is the time required for optimal reporter gene expression." (PMID 20195464, 2010). "HeLa cells, with similar levels of infection (15–20% of Gag-expressing cells, as assessed by flow cytometry), were then cocultivated with CD4+ lymphocytes." (PMID 20585562, 2010). "Recently it has been demonstrated that HIV-1 promotes CD4+ T cell infection by inserting CD40L into emerging viral particles and trans-activating B cells in a CD40 dependent manner." (PMID 20967291, 2010).